DUSP22 (dual specificity phosphatase 22)
Description:
Dual specificity phosphatase; can dephosphorylate both phosphotyrosine and phosphoserine or phosphothreonine residues. Activates the JNK signaling pathway. Inhibits T-cell receptor signaling and T-cell mediated immune responses, acting, at least in part, by inducing degradation of E3 ubiquitin ligase UBR2. Dephosphorylates and thereby induces 'Lys-48'-linked ubiquitination of UBR2, leading to proteasomal degradation of UBR2. Dephosphorylates and thereby inactivates tyrosine kinase LCK. Inhibits UBR2-mediated 'Lys-63'-linked ubiquitination of LCK. May play a role in B-cell receptor (BCR) signaling and B-cell function (By similarity).
Synonyms: JKAP; JSP-1; LMW-DSP2; MKP-x; JSP1; LMWDSP2; MKPX; VHX
Tractability: Small molecule: a structure with a bound ligand is known; a high-quality ligand is known. Antibody: its Gene Ontology location is reachable by antibodies, with high confidence. PROTAC: ubiquitination databases record sites on it; a small molecule that binds it is known.
Target class: Phosphatase; Serine/threonine/tyrosine protein phosphatase; Enzyme; Protein Phosphatase
Gene: Protein-coding gene on chromosome 6 (291,630 to 351,355, forward strand). Ensembl gene ENSG00000112679.
Subcellular location: Cytoplasm
Subcellular location (Human Protein Atlas): Nucleoplasm; Vesicles
Gene Ontology:
Molecular function: non-membrane spanning protein tyrosine phosphatase activity; protein tyrosine kinase binding; protein tyrosine kinase inhibitor activity; protein tyrosine phosphatase activity; protein tyrosine/serine/threonine phosphatase activity; protein serine/threonine phosphatase activity
Biological process: cellular response to epidermal growth factor stimulus; intracellular signal transduction; negative regulation of cell migration; negative regulation of focal adhesion assembly; negative regulation of T cell receptor signaling pathway; negative regulation of transcription by RNA polymerase II; positive regulation of JNK cascade; transforming growth factor beta receptor signaling pathway; cellular response to growth factor stimulus; negative regulation of cell adhesion; signal transduction
Cellular component: cytoplasm; filamentous actin; leading edge of lamellipodium; plasma membrane
Genetic constraint (gnomAD): Loss-of-function variants: 29 observed, 28.11 expected, observed/expected ratio (o/e) 1.03, 90% interval 0.77 to 1.41. The synonymous counts are far from expectation, so gnomAD's model fits this gene poorly and the ratio says little. Missense variants: 330 observed, 273.78 expected, observed/expected ratio (o/e) 1.21, 90% interval 1.1 to 1.32. Synonymous variants: 160 observed, 107.28 expected, observed/expected ratio (o/e) 1.49, 90% interval 1.31 to 1.7.
Homologues: Orthologues: chimpanzee DUSP22 (100% identical), mouse Dusp22 (91% identical), pig DUSP22 (89% identical), macaque DUSP22 (82% identical), rat Dusp22 (80% identical), guinea pig DUSP22 (75% identical), tropical clawed frog dusp22 (71% identical), dog DUSP22 (70% identical), zebrafish dusp22b (55% identical). Paralogues in human: DUSP15 (47% identical), SSH1 (31% identical), SSH2 (31% identical), SSH3 (31% identical), DUSP7 (29% identical), DUSP6 (29% identical), DUSP9 (28% identical), STYXL2 (27% identical), DUSP8 (27% identical), DUSP12 (26% identical), DUSP16 (26% identical), STYX (26% identical), and 19 more.
Diseases named in the same sentence as DUSP22 in open-access papers:
DUSP22 is named in the same sentence as 94 diseases in open-access papers, as found by Europe PMC text mining. Sharing a sentence is not in itself a finding about the gene and the disease. The quoted sentences say what the papers report.
Autoimmunity (12 papers, 2016 to 2025). The occurrence of an immune reaction against the organism's own cells or tissues. "While young DUSP22-deficient mice appear normal, aged (1-year-old) DUSP22 knockout mice develop spontaneous inflammation and autoimmunity." (PMID 39944077, 2025). "DUSP22-deficient animal models exhibit risks of autoimmunity, and downregulation of DUSP22 in patients exhibits a strong relationship with systemic lupus erythematosus (SLE) and inflammatory bowel disease (IBD)." (PMID 33053837, 2020). "Two atypical DUSPs, MKP-6 (DUSP14) and JKAP (DUSP22), are linked to T cell activation and autoimmunity." (PMID 31297117, 2019). "Several mouse studies on DUSP22 in autoimmune disorders have been reported." (PMID 39944077, 2025). "All these features tightly link the crucial roles of DUSP22 with autoimmune disorders, such as SLE." (PMID 33198301, 2020). "Our previous study indicates that JKAP (also named DUSP22) inhibits T-cell activation and that JKAP knockout mice develop spontaneous autoimmunity; therefore, we investigated whether JKAP downregulation is involved in SLE patients." (PMID 27557500, 2016). "No gene-disrupting mutations were identified for either paralog in hundreds of population controls, making it plausible that DUSP22B, which is expressed at variable dosage in humans, is functionally redundant with DUSP22 and could similarly play a protective role in autoimmunity." (PMID 34009325, 2021). "Notable genes of relevance on autosomes include DUSP22 on chromosome 6, which is known to activate JNK signaling in T cells and aged knockout mice show increased autoimmunity implicating immune system response." (PMID 35711915, 2022). "Recently, it has been reported that JKAP (DUSP22), as a member of DUSPs, activates TCR signaling and JKAP-knockout mice develop exacerbated autoimmunity through enhancing T-cell immune responses." (PMID 28725226, 2017). "Additionally, DUSP22-absent mice exerted aggravated inflammation and autoimmunity compared to wide-type mice and were more likely to develop experimental autoimmune encephalomyelitis (EAE)." (PMID 36209205, 2022).
anaplastic large cell lymphoma (10 papers, 2018 to 2025). Anaplastic large cell lymphoma (ALCL) is a rare and aggressive peripheral T-cell non-Hodgkin lymphoma, belonging to the group of CD30-positive lymphoproliferative disorders, which affects lymph nodes and extranodal sites. "Nevertheless, DUSP22 rearrangements present not only in ALK-negative anaplastic large cell lymphoma, but also in primary cutaneous anaplastic large cell lymphoma and lymphomatoid papulosis." (PMID 35406421, 2022). "Disease defining recurrent chimeric gene fusions from translocations, such as NPM/ALK or DUSP22/FRA7H in anaplastic large cell lymphoma is uncommon in mature T-Cell lymphomas." (PMID 35330161, 2022). "DUSP22 is a tumor suppressor gene, and rearrangements in this gene have been associated with favorable outcomes in patients with kinase-negative anaplastic large cell lymphoma." (PMID 40242470, 2025). "DUSP22 translocations are relatively specific for ALK-negative anaplastic large cell lymphomas." (PMID 35330161, 2022). "Rearrangement of the DUSP22 gene is also seen in a subset of systemic ALK-negative anaplastic large cell lymphoma (ALK-ALCL) and in about 20% of pcALCL." (PMID 36278991, 2023). "Interestingly, DUSP22-hypomethylated anaplastic large cell lymphomas with DUSP22 rearrangements are characterized by better prognosis which appears to be linked to the higher expression of costimulatory molecules and reduced PD1/PD1-L activity, and hence stronger immunogenicity." (PMID 31159473, 2019). "Finally, the DUSP22 gene fusion was reported to be related to anaplastic large-cell lymphoma." (PMID 29697361, 2018). "Declined expression of DUSP22 in t cell lymphomas has been discovered, which suggests that this phosphatase plays a role similar to a tumor suppressor gene in ALK-negative anaplastic large cell lymphomas." (PMID 35406421, 2022). "Research on systemic and cutaneous Dual Specificity Phosphatase-22 (DUSP-22) rearrangements in Anaplastic Lymphoma Kinase (ALK)-negative Anaplastic Large Cell Lymphoma (ALCL) has demonstrated positive CD58 expression, correlating with immune identification of the tumor and a favorable prognosis." (PMID 40365344, 2025).
inflammatory bowel disease (9 papers, 2017 to 2026). A spectrum of small and large bowel inflammatory diseases of unknown etiology. "Additionally, decreased levels of DUSP2, DUSP11, DUSP22, and DUSP28 are associated with human inflammatory bowel diseases." (PMID 42087139, 2026). "Recently, DUSP22 was described to contribute to inflammatory bowel disease." (PMID 32577795, 2020). "In human patients with inflammatory bowel disease (IBD), DUSP22 expression was inversely correlated with disease activity and with the levels of IL-17 and TNF in the inflamed mucosa." (PMID 31159473, 2019).
systemic lupus erythematosus (9 papers, 2016 to 2024). An autoimmune multi-organ disease typically associated with vasculopathy and autoantibody production. "In addition, DUSP22 knockout mice show enhanced T-cell-mediated immune responses and are more susceptible to experimental autoimmune encephalomyelitis (EAE); consistently, DUSP22 protein levels are decreased in T cells of human systemic lupus erythematosus (SLE) patients." (PMID 31151270, 2019).
autoimmune disease (8 papers, 2016 to 2026). A disorder resulting from loss of function or tissue destruction of an organ or multiple organs, arising from humoral or cellular immune responses of the individual to their own tissue constituents. "Taken together, UBR2-induced Lck trans-autophosphorylation and Lys63-linked ubiquitination were further enhanced by DUSP22 deficiency, leading to proinflammatory cytokines production and autoimmune disease." (PMID 38225265, 2024). "As a consequence of enhanced TCR signaling, increased T cell proliferation and cytokine production, DUSP22-deficient mice are more susceptible in models of autoimmune disease such as EAE and develop spontaneous inflammation and autoimmunity in old age." (PMID 31159473, 2019). "Besides DUSP22 downregulation in SLE patients, other DUSPs (DUSP2, DUSP7, DUSP10, and DUSP12) are also downregulated or mutated in human autoimmune diseases." (PMID 31766293, 2019). "Thus, our mechanistic insights on Lck activation and inactivation by UBR2 and DUSP22, respectively, may provide therapeutic strategies to reduce T-cell-mediated autoimmune disease." (PMID 38225265, 2024). "Downregulation of DUSP1, DUSP3, DUSP11, and DUSP22, as well as upregulation of DUSP4, DUSP6, and DUSP23 are involved in human autoimmune diseases." (PMID 42087139, 2026). "DUSP2, DUSP4, DUSP7, DUSP10, DUSP12, DUSP22, and DUSP23 are involved in human autoimmune diseases, including SLE." (PMID 31766293, 2019). "Since the down-regulation of DUSP22 expression in CD4+ T cells was also correlated with the presence and activity of Systemic Lupus Erythematodes (SLE) in human patients, DUSP22 is emerging as a biomarker for several autoimmune diseases." (PMID 31159473, 2019).
lymphoma (6 papers, 2019 to 2025). A malignant (clonal) proliferation of B- lymphocytes or T- lymphocytes which involves the lymph nodes, bone marrow and/or extranodal sites. "DUSP22, a known tumor suppressor gene in lymphomas, is mutated in both lymphomas as well." (PMID 40404986, 2025). "DUSP22 expression is associated with poorer survival in low-grade lymphomas." (PMID 39406235, 2024). "DUSP22 is a phosphatase that might be involved in the c-Jun N-terminal kinase signaling pathway and has been shown to be associated with lymphomas." (PMID 33607115, 2021). "The significance of these findings is further underscored by recent observations linking monoallelic 6p25.3 rearrangements with DUSP22 to lymphoma and leukemia." (PMID 40242470, 2025). "Recent reports highlight several examples, including SPATC1L in male infertility, PM20D1 in Alzheimer’s disease, and DUSP22 in lymphoma." (PMID 31155008, 2019). "In our results, some of the differentially methylated genes in EHMT2 + MCL cases have also been reported with recurrent genetic alterations in lymphoma, such as ALK, DUSP22, NCOR2, RORA, DLC1, JAG1/2, JAK1, NOTCH4, and CD1938–45." (PMID 34633777, 2021).
rheumatoid arthritis (6 papers, 2021 to 2026). A chronic, systemic autoimmune disorder characterized by inflammation in the synovial membranes and articular surfaces. "DUSP22 levels in synovium and serum are inversely correlated with inflammation and disease activity in patients with rheumatoid arthritis (RA)." (PMID 36765305, 2023). "A previous study reports that in serum of patients with rheumatoid arthritis, the hypomethylated regions in DUSP22 (another name of JKAP) gene and CYP2E1 gene are correlated with more active and erosive disease condition." (PMID 33083958, 2021).
schizophrenia (6 papers, 2018 to 2023). A major psychotic disorder characterized by abnormalities in the perception or expression of reality. "Altered DNA methylation of the DUSP22 gene mediated the association between prenatal famine exposure and schizophrenia in adult offspring." (PMID 37716973, 2023). "Third, only one mediation study has been conducted to date, which described altered DNA methylation of the DUSP22 gene as a potential mechanism underlying the association between prenatal famine exposure and schizophrenia in adult offspring." (PMID 37716973, 2023). "In the Dutch case-control sample, the association between DUSP22 promoter methylation and schizophrenia persisted after adjustment for genetic background (B = 0.741, p = 0.025)." (PMID 30131491, 2018). "In this sample, DUSP22 methylation was also significantly higher in patients independent of famine exposure (p = 0.025), suggesting that hypermethylation of DUSP22 is also more generally involved in schizophrenia risk." (PMID 30131491, 2018). "The results of this series of experiments suggest that altered transcriptional regulation of DUSP22 in response to famine is a schizophrenia susceptibility factor." (PMID 30131491, 2018). "In the postmortem brains, the association between DUSP22 promoter methylation and schizophrenia was attenuated after adjustment for genetic background (B = 0.13, t = 1.745, p = 0.083)." (PMID 30131491, 2018). "Moreover, methylation at the DUSP22 gene in brain tissue has been previously implicated in schizophrenia, Parkinson’s and Alzheimer’s disease, albeit in different directions depending on the brain region investigated." (PMID 35145228, 2022). "This supports the involvement of the DUSP22 gene in the etiology of schizophrenia in adults prenatally exposed to famine." (PMID 37716973, 2023). "For example, significant hypermethylation in the promoter of the schizophrenia candidate gene, such as DUSP22, was observed in the Chinese famine-exposed schizophrenia patients." (PMID 34881050, 2021). "In the postmortem tissue from the PFC, significant DUSP22 hypermethylation was also found in schizophrenia patients (N = 91) compared to unaffected individuals (N = 123)." (PMID 30131491, 2018). "DUSP22 methylation was also higher in postmortem prefrontal cortex (PFC) tissue of schizophrenia patients (N = 91; mean methylation = 0.40, sd = 0.10) compared to unaffected controls (N = 123; mean methylation = 0.37, sd = 0.13) (B = 0.35, p = 0.007)." (PMID 30131491, 2018). "Support for a direct relationship between famine exposure and DUSP22 methylation was obtained by depriving the fibroblasts of schizophrenia patients (N = 5) and controls (N = 5) from nutrition." (PMID 30131491, 2018). "DUSP22 hypermethylation in the same region was also significant in blood DNA samples of Dutch schizophrenia patients (N = 15, mean methylation = 0.43, sd = 0.10) compared to healthy controls (N = 49, mean methylation = 0.32, sd = 0.20, p = 0.03)." (PMID 30131491, 2018). "In the famine-exposed schizophrenia patients, we found significant hypermethylation of the dual specificity phosphatase 22 (DUSP22) gene promoter (Chr6:291687-293285) (N = 153, p = 0.01)." (PMID 30131491, 2018). "Ethnicity influenced the relationship between DUSP22 methylation and schizophrenia in the brain case-control sample (Schizophrenia by Race interaction: B = 0.680, p = 0.007)." (PMID 30131491, 2018). "DUSP22 was also related to schizophrenia, ZFP57 with autism, and FGFR2 with depression." (PMID 36091392, 2022). "This is in line with the stratified analyses for ethnicity that show an association between DUSP22 methylation and schizophrenia in the Caucasians only (B = 0.692, p = 0.002), and not in the African–Americans (B = −0.086, p = 0.436)." (PMID 30131491, 2018). "The authors reported that prenatally exposed adults with schizophrenia showed hypermethylation of the DUSP22 gene compared to non-exposed patients and healthy controls." (PMID 37716973, 2023).
schizophrenia (continued). "DUSP22 methylation was also significantly higher in Chinese schizophrenia patients independent of famine exposure (B = 0.07, p = 0.025)." (PMID 30131491, 2018). "In this sample, patients also had significant hypermethylation independent of famine exposure suggesting that DUSP22 hypermethylation is primarily involved in schizophrenia." (PMID 30131491, 2018). "After adjustment for genetic background, the relationship of DUSP22 methylation with famine and schizophrenia was only present in a selection of participants without the 35 participants with a genetic predisposition for low invariable methylation levels (N = 118, B = 0.028, p = 0.072)." (PMID 30131491, 2018).
Alzheimer disease (5 papers, 2016 to 2025). A progressive, neurodegenerative disease characterized by loss of function and death of nerve cells in several areas of the brain leading to loss of cognitive function such as memory and language. "Finally, two studies recently reported DUSP22 5′ region hypomethylation upon fire smoke exposure or hypermethylation in Alzheimer's disease." (PMID 27626696, 2016).
colorectal cancer (5 papers, 2017 to 2024). A primary or metastatic malignant neoplasm that affects the colon or rectum. "For example, a decrease in double-specific phosphatase 22 expression (DUSP22) was observed in colorectal cancer specimens, and the reduced expression of DUSP22 in stage IV patients was linked to poor survival rates." (PMID 36230757, 2022). "DUSP22 showed lower mRNA expression in colorectal cancer tissues compared to adjacent normal colonic mucosa." (PMID 36295658, 2022). "For example, downregulation of dual specificity phosphatase 22 (DUSP22) expression was observed in colorectal cancer specimens and reduced DUSP22 expression in stage IV patients was mainly exhibited poor survival outcome." (PMID 31055775, 2020).
diabetes (5 papers, 2020 to 2025). "FGFR2 associated with obesity and weight at birth and with adult obesity; DUSP22 related to diabetes and obesity, and ZFP57 related to nutrition/neonatal diabetes." (PMID 36091392, 2022). "DNA methylation of genes identified such as SLC2A9, HOOK2, LTF, and DUSP22 all have direct or indirect links to diabetes or obesity including immune or inflammatory regulatory pathways, signaling pathways, and clinical disorders related to diabetes and obesity." (PMID 32075680, 2020).
Obesity (5 papers, 2020 to 2023). Accumulation of substantial excess body fat. "We then examined the expression of DUSP22 in two obesity-associated NAFLD-HCC mouse models." (PMID 36209205, 2022). "DUSP22 was reported as an obesity candidate gene hypermethylated in omental visceral adipose tissue but not in subcutaneous adipose tissue of obese subjects." (PMID 36715159, 2023). "DUSP22 was an obesity candidate gene which was hypermethylated in obese subject." (PMID 32801562, 2020). "DUSP22 protein activate the JNK signaling pathway – regulating the phosphorylation state of several kinases in skeletal muscle and requiring for obesity." (PMID 32801562, 2020). "The effects of obesity were partly mediated by the differential methylation of LTF and DUSP22." (PMID 32075680, 2020).